FSTL4 (follistatin like 4)
Synonyms: KIAA1061
Tractability: Antibody: UniProt places it where antibodies can reach, with high confidence; UniProt predicts a signal peptide or a membrane-spanning region; its Gene Ontology location is reachable by antibodies, with medium confidence.
Gene: Protein-coding gene on chromosome 5 (133,196,455 to 133,612,688, reverse strand). Ensembl gene ENSG00000053108.
Subcellular location: Secreted
Subcellular location (Human Protein Atlas): Vesicles; Predicted to be secreted
Gene Ontology:
Molecular function: brain-derived neurotrophic factor binding; calcium ion binding
Biological process: cell differentiation; regulation of BMP signaling pathway
Cellular component: extracellular region; secretory granule
Genetic constraint (gnomAD): Loss-of-function variants: 17 observed, 57.78 expected, observed/expected ratio (o/e) 0.29, 90% interval 0.2 to 0.44. The upper end of that interval is the gene's LOEUF score, 0.44, which puts it in group 1 of 6, group 1 being the genes least tolerant of losing a copy. Missense variants: 745 observed, 928.48 expected, observed/expected ratio (o/e) 0.8, 90% interval 0.75 to 0.85. Synonymous variants: 354 observed, 383.33 expected, observed/expected ratio (o/e) 0.92, 90% interval 0.85 to 1.01.
Homologues: Orthologues: chimpanzee FSTL4 (99% identical), macaque FSTL4 (93% identical), pig FSTL4 (86% identical), mouse Fstl4 (84% identical), dog FSTL4 (84% identical), rat Fstl4 (83% identical), guinea pig FSTL4 (80% identical), rabbit FSTL4 (76% identical), tropical clawed frog fstl4 (62% identical), zebrafish fstl4 (54% identical). Paralogues in human: FSTL5 (57% identical), FSTL1 (11% identical), SPINK5 (11% identical), FST (8% identical), FSTL3 (6% identical), SPINK6 (2% identical).
Diseases named in the same sentence as FSTL4 in open-access papers:
FSTL4 is named in the same sentence as 7 diseases in open-access papers, as found by Europe PMC text mining. Sharing a sentence is not in itself a finding about the gene and the disease. The quoted sentences say what the papers report.
Hypertension (1 paper, 2014). The presence of chronic increased pressure in the systemic arterial system. "Variants in FSTL4 were modestly associated to human ischemic stroke, and a variant 70 kb from FSTL4 nominally to hypertension." (PMID 24497844, 2014).
parasitemia (1 paper, 2024). "When applied across all vaccinated groups, FSTL4 induction was significantly associated with reduced risk of incident parasitemia, even when adjusted for sex, site, baseline CSP-specific IgG, and baseline parasitemia." (PMID 38687615, 2024).
Stroke (1 paper, 2012). Sudden impairment of blood flow to a part of the brain due to occlusion or rupture of an artery to the brain. "FSTL4, which is a key modulator in muscle development, was specified as nominally associated with increased risk of stroke in a cardiovascular health study." (PMID 22384028, 2012).
cancer (4 papers, 2016 to 2024). A tumor composed of atypical neoplastic, often pleomorphic cells that invade other tissues. "In the aging model group, the genes that were highly expressed were mainly FOSB, HS3ST2, and FSTL4, and other genes related to tumors, cancer, and other diseases." (PMID 38191526, 2024). "However, in the aging model group, the genes that were highly expressed were mainly FOSB, HS3ST2, and FSTL4, which are related to tumors, cancer, and other diseases." (PMID 38191526, 2024). "For example, FSTL4 (a member of the follistatin-like proteins; FSTl1 instead of FSTL4) was identified as candidate gene affected by LOH in a murine cancer model." (PMID 27159447, 2016). "In addition to these, we also identified some novel genes among the 14-CpG markers that were not previously associated with cancer recurrences such as IFFO1, ALKAL1, FAHD1, FSTL4, SLC7A9, IQCJ-SCHIP1, CLDN11 and three other CpGs at intergenic regions." (PMID 34207933, 2021).
FSTL4 also shares sentences with these, for which no sentence is quoted: ischemic stroke (1 paper); osteoporosis (1); tumour (1).